FLNC (filamin C)
Description:
Muscle-specific filamin, which plays a central role in sarcomere assembly and organization. Critical for normal myogenesis, it probably functions as a large actin-cross-linking protein with structural functions at the Z lines in muscle cells. May be involved in reorganizing the actin cytoskeleton in response to signaling events (By similarity).
Synonyms: ABPL; FLN2; ABP-280; ABP280A; ABPA; ARVC15; CMD1PP; CMH26; MFM5; MPD4; RCM5
Tractability: Small molecule: a structure with a bound ligand is known. Antibody: UniProt places it where antibodies can reach, with high confidence; its Gene Ontology location is reachable by antibodies, with high confidence. PROTAC: UniProt records ubiquitination sites on it; ubiquitination databases record sites on it; its protein half-life has been measured.
Gene: Protein-coding gene on chromosome 7 (128,830,312 to 128,859,275, forward strand). Ensembl gene ENSG00000128591.
Subcellular location: Cytoplasm; Membrane; Cytoplasm, cytoskeleton; Cytoplasm, myofibril, sarcomere, Z line
Subcellular location (Human Protein Atlas): Cytosol; Plasma membrane
Pathways (Reactome):
Cell-Cell communication: Cell-extracellular matrix interactions
Gene Ontology:
Molecular function: ankyrin binding; cytoskeletal protein binding; protein binding; actin filament binding
Biological process: sarcomere organization; actin cytoskeleton organization; muscle cell development
Cellular component: cytoplasm; cytosol; focal adhesion; sarcolemma; costamere; cytoskeleton; membrane; sarcoplasm; Z disc
Genetic constraint (gnomAD): Loss-of-function variants: 88 observed, 247.7 expected, observed/expected ratio (o/e) 0.36, 90% interval 0.3 to 0.42. The upper end of that interval is the gene's LOEUF score, 0.42, which puts it in group 1 of 6, group 1 being the genes least tolerant of losing a copy. Missense variants: 2,824 observed, 3,835.8 expected, observed/expected ratio (o/e) 0.74, 90% interval 0.71 to 0.76. Synonymous variants: 1,413 observed, 1,590.6 expected, observed/expected ratio (o/e) 0.89, 90% interval 0.85 to 0.93.
Gene-disease validity (ClinGen):
ClinGen rates the evidence that FLNC causes each of these diseases.
dilated cardiomyopathy (autosomal dominant): Definitive. Cardiomyopathy which is characterized by dilation and contractile dysfunction of the left and right ventricles.
myofibrillar myopathy (autosomal dominant): Definitive.
Homologues: Orthologues: chimpanzee FLNC (99% identical), pig FLNC (99% identical), guinea pig FLNC (98% identical), mouse Flnc (98% identical), rat Flnc (98% identical), dog FLNC (98% identical), rabbit FLNC (94% identical), tropical clawed frog flnc (87% identical), zebrafish flncb (84% identical), zebrafish flnca (79% identical). Paralogues in human: FLNA (71% identical), FLNB (68% identical), MACF1 (15% identical), DST (14% identical), PLEC (13% identical), SPTBN1 (12% identical), SPTB (12% identical), SYNE1 (11% identical), SYNE2 (11% identical), PKHD1L1 (11% identical), SPTBN2 (11% identical), SPTBN5 (11% identical), and 24 more.
Diseases named in the same sentence as FLNC in open-access papers:
FLNC is named in the same sentence as 154 diseases in open-access papers, as found by Europe PMC text mining. Sharing a sentence is not in itself a finding about the gene and the disease. The quoted sentences say what the papers report.
cardiomyopathy (81 papers, 2017 to 2026). A disease of the heart muscle or myocardium proper. "Currently, FLNC mutations contribute to all types of cardiomyopathies—hypertrophic, dilated, arrhythmogenic and restrictive." (PMID 39315490, 2025). "In striated muscle, the actin-binding protein filamin C (FLNC) is a key protein whose variants causative for a wide range of cardiomyopathies and musculoskeletal pathologies." (PMID 40312381, 2025). "Only mutations in FLNC result in muscle disorders, including muscular dystrophies, myofibrillar myopathy, distal myopathy, and cardiomyopathy." (PMID 41306978, 2025). "In humans, heterozygous mutations of the FLNC gene cause cardiomyopathy, and animal models of hereditary cardiomyopathy are required to study possible therapeutic agents and approaches." (PMID 40003875, 2025). "In recent years, the role of FLNC gene variants in cardiomyopathies has received increasing attention." (PMID 41464097, 2025). "In humans, heterozygous mutations in the FLNC gene can cause various types of cardiomyopathies: arrhythmogenic (ACM), dilated (DCM) and restrictive (RCM)." (PMID 40003875, 2025). "Among them, abnormalities of Filamin C, secondary to mutations on the FLNC gene, are associated with cardiac disorders that result in diverse cardiomyopathy phenotypes." (PMID 40524707, 2025). "Our study investigates FLNC-related cardiomyopathies, revealing phenotypic diversity linked to mutation location and type." (PMID 41440871, 2025). "This case highlights the importance of identifying genetic causes, particularly FLNC mutations, in young patients with unexplained cardiomyopathy." (PMID 40524707, 2025). "A ring-like LGE pattern has also been reported, although less frequently than in cardiomyopathies associated with DSP or FLNC mutations." (PMID 40869437, 2025). "FLNC mutations contribute to various types of cardiomyopathies and myopathies through potentially different molecular mechanisms." (PMID 39315490, 2025). "As a whole, the Ala1186Val variant in the FLNC gene provokes a severe myopathy with contractures, respiratory involvement, and cardiomyopathy due to protein aggregation in patients’ muscles." (PMID 38397924, 2024). "As discussed by Brodehl and colleagues, this aberrant aggregation is linked to a variety of myopathies and cardiomyopathies, similar to what is observed with FLNC mutations." (PMID 38397924, 2024). "To recapitulate the human pathogenesis, we generated FLNC-deficient hiPSC lines using the CRISPR/CAS9 system as a model of FLNC-related cardiomyopathy." (PMID 38334670, 2024). "Filamin C (FLNC), recently identified as a causative gene of cardiomyopathy, is widely expressed in cardiomyocytes and is involved in signal transduction between the sarcomere and the plasma membrane." (PMID 39734947, 2024). "Cardiomyopathies linked to mutations in the Flnc gene, encoding Filamin C, an actin-binding protein crucial for sarcomeric stability, pose a higher risk of cardiovascular pathology in men." (PMID 38529333, 2024). "Filamin C-related disorders include myopathies and cardiomyopathies linked to variants in the FLNC gene." (PMID 38397924, 2024). "FLNC has been implicated in inherited formsof cardiomyopathy and as the cause of DCM with life-threatening ventriculararrhythmia." (PMID 39618871, 2024). "Truncating FLNC variants associated with dilated and arrhythmogenic cardiomyopathies are loss-of-function (LoF) mutations, causing haploinsufficiency." (PMID 38334670, 2024). "Loss of FLNc leads to severe impairment in myogenesis and in the maintenance of muscle structural integrity, resulting in skeletal myopathy and cardiomyopathy." (PMID 36943452, 2023). "Subsequently, FLNC variants have been found to be associated with different cardiomyopathies (e.g., HCM, RCM) and several skeletal muscle disorders." (PMID 37240454, 2023). "The FLNC gene encodes the protein Filamin C, mainly associated wit cardiomyopathies following an AD pattern of inheritance." (PMID 37035729, 2023).
cardiomyopathy (continued). "Possible inheritable proarrhythmic genetic substrate in the form of cardiomyopathy-causative variants of FLNC, encoding filamin C, has been reported in patients with arrhythmic MVP." (PMID 37144062, 2023). "To date, hundreds of unique FLNC variants have been linked to cardiomyopathies, including many in arrhythmogenic cardiomyopathy and multiple FLNC-truncating mutations in patients with DCM." (PMID 35055055, 2022). "While the first description of FLNC variants associated with isolated cardiomyopathy is recent (2014), a large number of FLNC variants have since been reported." (PMID 36066120, 2022). "At present, variants in FLNC are associated with either neuromuscular phenotype (MFM or DM) or different types of cardiomyopathies; dilated, arrhythmogenic, hypertrophic, or restrictive." (PMID 36104822, 2022). "Next, we aimed to use the Drosophila model to assess the pathogenicity of human FLNC variants identified in patients affected by cardiomyopathies." (PMID 36066120, 2022). "The study group included twelve children presenting with early-onset cardiomyopathy and myopathy due to FLNC pathogenic and likely-pathogenic variants." (PMID 36104822, 2022). "FLNC is one of the few genes associated with all types of cardiomyopathies, but it also underlies neuromuscular phenotype." (PMID 36104822, 2022). "Mutations in FLNC, one of the three filamin genes in humans, have recently been implicated in dominant cardiomyopathies, but the underlying mechanisms are not well understood." (PMID 36066120, 2022). "Cytoskeletal protein variants include variants in desmin, lamin A/C, titin, myosin heavy and light chain, junctophilin, nucleoporin, nesprin, and filamin C. These cytoskeletal protein variants have a strong association with the development of cardiomyopathy." (PMID 35159226, 2022). "In humans, more than 325 unique sequence variants in FLNC are known (mainly affecting the longer isoform NM_001458.5), and not always resulting in distinct cardiac phenotypes in human cardiomyopathy." (PMID 33557094, 2021). "We investigated stability and fold integrity of FlnC mutant Q2058R implicated in cardiomyopathy located in the Ig‐like domain 19 of FlnC (FlnC‐d19, inset)." (PMID 33140490, 2021). "Variants in the FLNC gene that have been previously reported in individuals with myopathy or cardiomyopathy." (PMID 33802723, 2021). "Recently, the FLNC gene encoding the sarcomeric protein filamin C has gained special interest since FLNC mutations were found in several distinct and possibly overlapping cardiomyopathy phenotypes." (PMID 33557094, 2021). "Recent studies have revealed numerous mutations in the FLNC gene causing familial and sporadic myopathies and cardiomyopathies with marked clinical variability." (PMID 32887649, 2020). "Until now more than 200 dominant human mutations in the FLNC gene have been identified to be associated with a great variety of myopathies and cardiomyopathies." (PMID 32887649, 2020). "FLNC still attracts high research interest due to new loss-of-function pathogenic isoforms identified in patients with severe form of myopathies and cardiomyopathies." (PMID 33202721, 2020). "Variants in FLNC are known to cause cardiomyopathy, and we recently reported the frameshift variant p.Phe1626Serfs*40 in FLNC36 with opposite direction of effects on the R amplitude in lead V1 and myocardial infarction to those of p.Ala2397Val." (PMID 31641117, 2019). "More interestingly, FLNC‐cardiomyopathy patients rarely had skeletal myopathy, which is another pathological result of FLNC mutation." (PMID 30411535, 2018). "A second major Z-disc-associated actin-binding protein that was shown to cause cardiomyopathy when mutated is filamin C. Missense mutations of filamin C cause familial restrictive cardiomyopathy and lead to a loss of filamin C signal at the Z-disc." (PMID 29869751, 2018).
cardiomyopathy (continued). "FLNC mutations in humans and mice cause hypertrophic cardiomyopathy and myofibrillar myopathy, a form of muscular dystrophy with concurrent cardiomyopathy." (PMID 28296976, 2017). "This study investigates FLNC mutations in Chinese cardiomyopathy patients." (PMID 41440871, 2025). "Mutations in the FLNC gene are known to cause myopathies and cardiomyopathies in humans." (PMID 40003875, 2025). "Since FLNC‐associated cardiomyopathies have a well‐proved increased risk of arrhythmic events, the combination of electrophysiological studies with expression analysis can uncover the bases for ion channel disfunction in patients with different types of FLNC mutations." (PMID 39315490, 2025). "Recently, FLNC has also been identified as a causative gene in the autosomal dominant form of various cardiomyopathies such as hypertrophic cardiomyopathy (HCM), dilated cardiomyopathy (DCM), restrictive cardiomyopathy, arrhythmogenic cardiomyopathy, and non-compaction left ventricle cardiomyopathy." (PMID 39734947, 2024). "Thus, FLNC homozygous knockout (FLNCKO) hiPSC-CMs represent an appropriate human cell model with which to study FLNC biology in the heart and the effects of loss-of-function (LoF) mutations in FLNC cardiomyopathy." (PMID 38334670, 2024). "More recently, FLNC variants have also been associated with isolated cardiomyopathies." (PMID 38397924, 2024). "Therefore, in this study, we used CRISPR-Cas-engineered hiPSC-derived FLNC knockout cardiac myocytes as a model of FLNC cardiomyopathy to determine pathogenic mechanisms and to examine structural changes caused by FLNC deficiency." (PMID 38334670, 2024). "Patients with an LVEF percentage between 40 and 50% and with specific forms of cardiomyopathy, such as those due to genetic mutations (e.g., Lamin A/C, filamin-C, and phospholamban), arrhythmogenic LV CMP, or hypertrophic CMP, may require ICD therapy." (PMID 38786970, 2024). "In conclusion, FLNC variants are associated with different cardiomyopathies." (PMID 36935760, 2023). "FLNC variants have been shown to play a vital role in the pathogenesis of cardiomyopathies." (PMID 37461109, 2023). "In addition, FLNC variants have been associated with the pathogenesis of other cardiomyopathies, e.g., ACM." (PMID 36935760, 2023). "Studies carried out on filamin C revealed that mutations in FLNC can lead to cardiomyopathies." (PMID 35735803, 2022). "However, immunohistochemical assessments of cardiomyopathy patients with FLNC missense variants reported the loss of filamin C from the intercalated disc." (PMID 33802723, 2021). "At sarcomeric z-discs, filamin C interacts with various proteins partially linked to inherited cardiomyopathies like calsarcins (Involved in HCM), myopalladin (linked to RCM), cypher (linked to ARVC and DCM), actin (linked to DCM), myotilin, myopodin, and others." (PMID 33557094, 2021). "Patients with mutated Filamin C gene demonstrate high incidence of cardiomyopathy." (PMID 34707599, 2021). "Mutations in FlnC give rise to skeletal muscle diseases and cardiomyopathies." (PMID 33140490, 2021). "As ~ 30% of affected myofibrillar myopathy patients carrying FLNC mutations presented with both skeletal myopathies and unspecified forms of cardiomyopathy, screening for FLNC mutations has been included in the genetic diagnosis of inherited cardiomyopathies since 2012." (PMID 33941202, 2021). "Mutations of FLNC result in cardiomyopathy and muscle weakness." (PMID 32295012, 2020). "Although it remains vague the precise mechanisms of how FLNC mutations and subsequent protein alterations affect different and partially overlapping cardiac phenotypes, it becomes increasingly clear that FLNC variants are found in and are associated with various forms of human cardiomyopathies." (PMID 33557094, 2021).
cardiomyopathy (continued). "Compared to cardiomyopathies caused by variants in DSP, PKP2, FLNC, and LMNA genes, TTN-CMP and sarcomeric gene-related cardiomyopathies tend to exhibit a similar burden of HF events but a generally lower arrhythmogenic profile." (PMID 41329234, 2025). "The GWAS of NT-proBNP levels identified cardiomyopathy- or heart failure-associated genetic loci (eg, HSPB7/CLCNKA, CDKN1A, TTN, FLNC, and BAG3)." (PMID 41054850, 2025). "Ring-like mid-wall or subepicardial LGE is suspicious for Desmoplakin (DSP) or Filamin C (FLNC) cardiomyopathies." (PMID 40429571, 2025). "Filamin C is a key actin-binding protein involved in cardiomyopathies and musculoskeletal disorders." (PMID 40312381, 2025). "In inherited cardiomyopathies, specific gene mutations (e.g., LMNA, DSP, DSG2, RBM20, FLNC, PLN) are associated with an increased risk of life-threatening arrhythmias, supporting early ICD implantation in some phenotypes." (PMID 40725457, 2025). "High-risk features for each cardiomyopathy phenotype (HCM, DCM, ARVC) and gene-specific (Filamin C (FLNC), desmoplakin (DSP), RNA binding motif protein 20 (RBM20)) high-risk features are elaborated on in Chapter 7 of the ESC guideline." (PMID 40227490, 2025). "Given the significant impact of FLNC mutations on cardiac function, this study aimed to characterize the genetic and clinical features of FLNC-related cardiomyopathy in a cohort of Chinese patients." (PMID 41440871, 2025). "While first identified as causative in myofibrillar myopathy, recent evidence reveals a key role for FLNC in cardiomyopathy pathogenesis." (PMID 38438525, 2024). "Filamin-C (FLNC) maintains cardiac muscle structural integrity due to its actin-binding capabilities; mutations in this protein are often tied to cardiomyopathies." (PMID 38559672, 2024). "However, among MVP patients with mild MR, we also highlight a global, multi-segment pattern of interstitial fibrosis which may underline a diffuse myopathic process initially proposed in genetic studies reporting mutations in cardiomyopathy genes (FLNC, LMNA, ALPK3A)." (PMID 39477155, 2024). "To date, FLNC variants have been associated with different disorders, ranging from skeletal muscle myopathies (MFM, DM or CM) to cardiomyopathies (MIM# 102565)." (PMID 38397924, 2024). "There was an excess burden of splice-disrupting variants in PKP2 (5.9%), FLNC (2.7%), TTN (2.8%), MYBPC3 (8.2%) and MYH7 (1.3%), in distinct cardiomyopathy subtypes, and KCNQ1 (3.6%) in long QT syndrome." (PMID 37821546, 2023). "They suggest that truncation variants in FLNC are prevalent in DCM, while missense or small in frame deletions are seen in other types of cardiomyopathies." (PMID 36935760, 2023). "The aim of this study was to evaluate the relevance of using Drosophila melanogaster as a new animal model to study FLNC-related cardiomyopathies." (PMID 36066120, 2022). "Currently, FLNC, together with TTN, are the only two genes associated with all types of cardiomyopathies, including arrhythmogenic (ACM), dilated (DCM), hypertrophic (HCM), and restrictive (RCM) ones." (PMID 36104822, 2022). "Subsequently, the application of next-generation sequencing technology resulted in multiple reports on the role of FLNC in different types of cardiomyopathies." (PMID 36104822, 2022). "Specifically, mutations in FLNC were initially only linked to myofibrillar myopathy (MFM), but are now increasingly found in various forms of human cardiomyopathy." (PMID 33557094, 2021). "This review will focus on six key Z-disc proteins: α-actinin 2, filamin C, myopalladin, myotilin, telethonin and Z-disc alternatively spliced PDZ-motif (ZASP), which have all been linked to myopathies and cardiomyopathies." (PMID 33802723, 2021). "Through our work, we have showed that, despite sharing the common role of actin-binding and crosslinking proteins, ACTN2, FLNC and DMD mutations can cause different types of cardiomyopathies, ranging from HCM to RCM." (PMID 32824180, 2020).